IL10 (interleukin 10)
Diseases named in the same sentence as IL10 in open-access papers (continued):
Sharing a sentence is not in itself a finding about the gene and the disease.
acute lymphoblastic leukemia (18 papers, 2012 to 2025). Leukemia with an acute onset, characterized by the presence of lymphoblasts in the bone marrow and the peripheral blood. "This study examined the impact of TNFα (G308A) and IL10 (G1082A) polymorphisms at promoter regions in relation to the overall survival of 105 children (0 ≤ 18 years) with acute lymphoblastic leukemia (ALL) for a period of 126 months, treated according to the protocol GBTLI99." (PMID 23213548, 2012). "IL-10 is known to be expressed by Tregs, regulate CD8+ T cell responses, inhibit activity of myeloid cells, and be implicated in relapse of CAR T therapy in acute lymphoblastic leukemia." (PMID 38085642, 2023). "Interestingly, BMP4 resulting from acute lymphoblastic leukemia can upregulate the expression of interleukin (IL)-10 and promote the polarization of M1-like macrophages to the M2 phenotype." (PMID 35832407, 2022). "In addition, baicalin reduced the survival of peripheral blood leukocytes (PBLs) in individuals suffering from acute lymphoblastic leukemia (ALL), increased IFNγ production in PBLs and decreased the production of TNFα and IL-10 in bone marrow cells (BMCs) in ALL patients." (PMID 39911847, 2025). "Interestingly, in acute lymphoblastic leukemia, BMP4 can upregulate the expression of interleukin (IL)-10 and promote the polarization of M1-like macrophages to the M2 phenotype." (PMID 35832407, 2022). "Exosomes extracted from patients with acute lymphoblastic leukemia (ALL) induced apoptosis in T lymphocytes and modulated the T‐cell profile to become Treg through the upregulation of FOXP3, IL‐10 and TGF‐β." (PMID 39611045, 2024). "The novelty of this work is the association of DAMPs (HMGB1) and inflammatory mediators (IL-8, IL-10, IL1-β, and MCP-1) in the development of systemic inflammatory response (SIRS) in pediatric patients with newly diagnosed acute lymphoblastic leukemia (ALL) and no apparent clinical infection." (PMID 40868835, 2025).
chronic heart failure (18 papers, 2011 to 2025). "Linggui Zhugan Decoction significantly inhibited the elevation in the levels of serum IL6, IL18, and IL-10 of the chronic heart failure rats." (PMID 32508942, 2020). "It was also found that catechin ameliorates cardiac dysfunction, in a rat model of chronic heart failure, by regulating the unbalanced level of IL-17/IL-10." (PMID 27681382, 2016). "Vitamin D3 supplementation was found to reduce the proinflammatory cytokine tumor necrosis factor α and enhance the anti-inflammatory interleukin 10, in a cohort of subjects with congestive heart failure." (PMID 23029606, 2012). "Patients with advanced congestive heart failure (New York Heart Association Class III and IV) also showed low IL-10 to TNF-α ratio." (PMID 21949832, 2011). "Vitamin D supplementation of congestive heart failure patients significantly increased serum concentrations of anti-inflammatory cytokine IL-10 and suppressed TNF-α synthesis over a nine month period." (PMID 21600051, 2011). "Unlike previous studies in chronic heart failure, where IL-10 was associated with a reduction in CD4+CD28null T cell frequencies, in ASCAD, its increase appears insufficient to counteract the inflammatory burden imposed by accumulated senescent T cells." (PMID 40508061, 2025). "Finally, based on the previous studies, it seems that moderate- to high-intensity endurance training can reduce IL-6 and TNF-α, and increase IL-10 in elderly healthy and patient with chronic heart failure male individuals." (PMID 33936044, 2021). "On the contrary, anti-inflammatory cytokines such as IL-10 may neutralize inflammation in chronic heart failure." (PMID 31384408, 2019). "In a mouse model of chronic heart failure, Treg cells secreted high levels of TGF-β, and only miniscule amounts of IL-10, which stimulated cardiac fibrosis." (PMID 32269577, 2020). "In a randomized control trial in congestive heart failure patients, vitamin D supplementation significantly reduced the concentration of pro-inflammatory cytokine, TNF-α, with an upregulation in IL-10 levels." (PMID 27271180, 2016). "We additionally identified that short-term endurance training at moderate intensities and the combination of endurance, strength, balance, and flexibility training increase plasma IL-10 and reduce plasma IL-6 and TNF-α in healthy elderly adults and male patients with chronic heart failure." (PMID 33936044, 2021).
chronic hepatitis B (18 papers, 2011 to 2022). "Genetic polymorphisms of several inflammatory cytokines, including TNF-α and IL-10, have been associated with chronic hepatitis B (CHB) progression, although with contradicting results." (PMID 36052277, 2022). "According to a pioneer study by Dr. Maini and her colleagues in 2012, IL-10 levels in plasma and liver inflammation levels of chronic hepatitis B patients were positively correlated, suggesting that the elevation of IL-10 levels is a protective mechanism." (PMID 35769476, 2022). "IL-10 has been found to be abundant in chronic hepatitis B (CHB) patients, which indicates that the effect of Th2-type cytokines is stronger than that of Th1-type cytokines." (PMID 34908456, 2021). "In patients with acute and chronic hepatitis B, the expression of IL-10 also affects their prognosis." (PMID 32912361, 2020). "Enhanced serum levels of IL-10 have indeed been described in chronic hepatitis B, particularly in the so-called immune activation phase." (PMID 31608071, 2019). "In the current study we observed the level of IL-10 was significantly lower in chronic hepatitis B patients with minor stress than patients with major stress(t = 6.538; p = 0.000)(Figure." (PMID 25144199, 2014). "IL-10 and IFN-γ are important cytokines involved in chronic HBV infection, as level of IL-10 and IFN-γ associated greatly with course of chronic hepatitis B." (PMID 25144199, 2014). "Our findings indicate that heterogeneity in the promoter region of the IL-10 gene has a role in determining the initial response of chronic hepatitis B to IFN-α therapy." (PMID 21251301, 2011). "It is no doubt that regulatory T cells can perform negative regulation by means of IL-10, and this has been confirmed for chronic hepatitis B. B10 cells exerted dysregulation in T cell function through IL-35 dependent mechanism and depend on cell-to-cell contact style." (PMID 35769476, 2022). "From a practical point of view, the assessment of plasma IL-10 levels in chronic hepatitis B acute exacerbation may provide an early predictive marker for progression to HBV-ACLF." (PMID 25147572, 2014). "The assessment of plasma IL-10 levels in chronic hepatitis B acute exacerbation may provide an early predictive marker for progression to HBV-ACLF." (PMID 25147572, 2014). "A considerable amount of data suggests that a switch from a predominantly type-1 cytokine-response pattern (e.g., relatively higher levels of IFN-γ) to a predominantly type-2 cell pattern (e.g., relatively higher IL-10) could impact on chronic hepatitis B progression." (PMID 25144199, 2014).
cyst (18 papers, 2009 to 2025). A sac-like closed membranous structure that may be empty or contain fluid or amorphous material. "Compared with BALB/c mice, FVB mice is a more favorable host for C. sinensis on the basis of cyst formation in bile ducts because they have increased production of Th2-associated anti-inflammatory cytokines, including IL-4, IL-5, IL-13, IL-10 and TGF-β." (PMID 28784165, 2017). "In contrast, equivalent numbers of IL-10-deficient BMDMs were unable to stimulate cyst cell proliferation." (PMID 27491076, 2016). "The levels of IFN-γ, IL-1β, IL-2, IL-4, IL-10, IL-12, and IL-13, in contrast, were significantly higher in pus than in cyst fluid." (PMID 35965529, 2022). "But during cyst establishment and growth, there is a switch to a Th2 response by secreted IL-4, IL-5, IL-6, IL-10 and so on, which is beneficial to parasite survival." (PMID 35360110, 2022). "We hypothesize that inhibition of high but not low level IL-10 is a reflection of the parasite's need to ensure appropriate amounts of IL-10 that avoid immunopathology and permit cyst formation, favoring long-term persistence in the host." (PMID 19859561, 2009). "Supporting this, animal models and patient samples have demonstrated upregulation of M2 macrophage‐related genes (Arg1, Ym1) and cytokines (IL‐10, TGF‐β) at lesion sites, with their mRNA levels positively correlated with cyst diameter and growth rate." (PMID 40921168, 2025). "In turn, IL-4 stimulates LTC4 generation and cyst-LTs release, including LTC4, while IL-10 enhances LTB4 production and release." (PMID 39843578, 2025). "In terms of cyst size and cyst volume, IL6 expression was positively correlated with cyst size (r = 0.22, P = 0.013) and cyst volume (r = 0.25, P = 0.005), and IL10 expression was also positively correlated with the cyst size (r = 0.24, P = 0.006) and cyst volume (r = 0.26, P = 0.002)." (PMID 38965454, 2024). "Mice were infected with a cyst-forming strain (ME49) of T. gondii, and levels of inflammatory mediators (IFN-γ and nitric oxide), anti-inflammatory cytokines (IL-10 and TGF-β), neuronal damage, and β-amyloid plaque deposition were examined in brain tissues and/or in BV-2 microglial cells." (PMID 22470449, 2012). "However, the increased expression of inflammatory mediators (and conversely, lower levels of the regulatory molecule, IL-10), were seen around some, but not all, cyst types; the differences between untreated and PZQ-treated cysts were significant only in cysts that demonstrated BBB disruption." (PMID 25774662, 2015).
glomerulonephritis (18 papers, 2014 to 2024). A renal disorder characterized by damage in the glomeruli. "Another study evaluated the relevance of cytokines and immune globulin with glomerulonephritis in IgAV children and observed IgA1 levels in serum galactose deficiency and IgA, IgG, IgM, IL-6, IL-8, and IL-10 complex levels in urine were predictors of glomerulonephritis in IgAV children." (PMID 35935867, 2022). "However, IL-10 deficiency in MRL.Faslpr mice led to disease exacerbation with more severe glomerulonephritis and higher mortality." (PMID 31546763, 2019). "Deficiency in IL-10 expression leads to exacerbate glomerulonephritis in transgenic mice." (PMID 27219334, 2016). "MCP-1, IL-6 and IL-10 plasma levels showed a significant increase in mice with LPS-induced glomerulonephritis compared to control mice." (PMID 37475889, 2023). "Immune modulation with IL-4 and IL-10 prevented crescent formation and glomerular injury in experimental glomerulonephritis." (PMID 34205404, 2021). "It has been shown in different models of glomerulonephritis that increased IL-10 promotes deposition of mesangial immune complexes, glomerular mesangial cell proliferation, and albuminuria, which aggravates kidney injury." (PMID 25302946, 2014). "Additionally, continuous blockade of IL-10 from birth delays the onset of autoantibody production and disease symptoms, such as proteinuria and glomerulonephritis." (PMID 38665907, 2024). "These proteins mapped to the following immune pathways “interleukin-10 signalling”, “glomerulonephritis”, “regulation of granulocyte chemotaxis”, “positive regulation of leukocyte chemotaxis”, “positive regulation of leukocyte migration”, and “inflammation” (FDR-corrected p ≤ 0.0337)." (PMID 38762535, 2024). "Conversely, other studies showed that IL-10, even during glomerulonephritis and 5/6 nephrectomy, could have a protective effect." (PMID 25302946, 2014). "Immunohistochemistry analysis showed that TNF-α, IL-6 and IL-10 were mainly expressed by mesangial cells and infiltrating macrophages in the glomeruli, as well as in the tubulointerstitial area and endothelium during the course of tubulointerstitial and glomerular nephritis in ECM." (PMID 38787228, 2024).
ileitis (18 papers, 2009 to 2025). "Interestingly, T. gondii infection in a model of IL-10 deficient intraepithelial lymphocyte transfer or NKT cell deficient (Jalpha281(-/-) mice had reduced ileitis with IL-10 expression." (PMID 31057534, 2019). "CB2R activation on Tregs enhances suppressive function and IL-10 secretion, attenuating murine ileitis by improving histological scoring and decreasing inflammatory cytokine expression." (PMID 37868958, 2023). "GLP-2 treatment reduced levels of pro-inflammatorycytokines (IFN-γ, TNF-α, and IL-1β) and induciblenitric oxide synthase, with increased levels of IL-10 in ileitis andcolitis models." (PMID 37491005, 2023). "MiR-106a knockout attenuated chronic murine ileitis via promoting Treg induction and suppressive function and IL-10 production." (PMID 32733020, 2020). "Upon ileitis induction, serum IL-10 concentrations increased in either hma mice, but less distinctly in P. aeruginosa infected mice as compared to uninfected controls (p < 0.001)." (PMID 28115993, 2017). "The anti-inflammatory cytokine IL-10 increased multifold upon ileitis induction, but interestingly more distinctly in P. aeruginosa infected as compared to uninfected controls." (PMID 28115993, 2017). "The failure of VSL#3 in the context of ileitis together with the observed reduction of cecal inflammation in IL-10−/− mice is consistent with clinical data showing effective probiotic treatment mostly in the context of UC and pouchitis patients." (PMID 19197385, 2009). "Intriguingly, susceptibility to ileitis in SKG mice could be mitigated by the ASF miniconsortium, which regulated Il23a and ER stress and upregulated Il10, preserving goblet cells and ZO-1+ tight junctions." (PMID 40762957, 2025). "Furthermore, higher apoptotic cell numbers, but lower anti-inflammatory IL-10 concentrations were assessed in the liver of Psae as compared to mock treated mice with ileitis." (PMID 30761129, 2019). "Interestingly, the anti-inflammatory cytokine IL-10 increased multifold upon ileitis induction in either mice (p < 0.05 and p < 0.001, respectively), but more distinctly in P. aeruginosa infected as compared to uninfected hma mice (p < 0.05)." (PMID 28115993, 2017). "With regard to anti-inflammatory cytokines, toxoplasmic ileitis is associated only circumstantially with defective TGF-β signalling but IL-10 plays a key role in ameliorating ileitis; a normally non-pathogenic dose (20 cysts) of T. gondii can kill mice lacking IL-10." (PMID 26053862, 2015). "Furthermore, significantly higher amounts of the anti-inflammatory cytokine IL-10 were found in the ilea (p<0.01-0.001), MLNs (p<0.01-0.005) and spleens (p<0.05-0.01) after either treatment regimen compared to Placebo controls with ileitis." (PMID 21151942, 2010). "Our results showed that MIF mediated T. gondii-induced ileitis does not affect IL-4 and increase IL-10 and TGF-β expression." (PMID 21977228, 2011).
lung adenocarcinoma (18 papers, 2014 to 2025). A carcinoma that arises from the lung and is characterized by the presence of malignant glandular epithelial cells. "Q56* nonsense mutation in IL-10, that has been seen in lung adenocarcinoma, is observed to abolish the association of IL-10 with A2M." (PMID 25056661, 2014). "A microarray analysis of the B-1 lymphocytes revealed that IL-10 deficiency is associated with down-regulation of the genes that code for claudin-10, a protein that is involved in cell-to-cell contact and that has been linked to lung adenocarcinoma." (PMID 29145406, 2017). "In addition, lung adenocarcinoma patients increased both plasma concentrations of IL-2, IL-4, IL-6, and IL-10, and proportions of Latency Associated Peptide (LAP) TGF-β subset of CD4+CD25+CD127− Treg cells, which overexpressed LAP TGF-β." (PMID 26582240, 2015). "Peritumoral AMs, which promote tumor growth by secreting IL‐10 and CCL2, have been implicated in poor prognosis in patients with lung metastases of non‐pulmonary origin and those with primary lung adenocarcinoma." (PMID 40051246, 2025). "Our study uniquely identified IL-1RA as a potential risk factor for lung adenocarcinoma and revealed that MCP-1, IL-10, IL-13, and TRAIL were significant factors for lung squamous cell carcinoma." (PMID 39132165, 2024). "In advanced lung adenocarcinoma, high expression of IL-10 receptor 1 correlates with worse prognosis, while IL-10 expression by T-regulatory cells inhibits apoptosis through Programmed death-ligand 1 inhibition." (PMID 33526761, 2021). "Increased levels of IL-10 are also supported in female lung adenocarcinoma patients and, although IL-10 has anti-inflammatory and anti-immune activities, studies have suggested a dual role in cancer." (PMID 33526761, 2021). "The importance of Th2 cytokines, including IL-4, IL-10, and IL-13, in the regulation of the protumor functions of TAMs has also been demonstrated in human lung adenocarcinomas." (PMID 26242181, 2015). "In lung adenocarcinoma patients, compared with smoking subjects, the concentrations of IL-2, IL-4, IL-6, and IL-10 were increased." (PMID 26582240, 2015). "Our results showed higher levels of proinflammatory (IL-2 and IL-6) and anti-inflammatory (IL-4 and IL-10) cytokines in lung adenocarcinoma patients compared with smoking subjects." (PMID 26582240, 2015). "Thus, a reduced expression of IL-1β, TNF-α, and IL-6 and an enhanced expression of IL-10 were observed in lung adenocarcinoma in mice treated with zotarolimus combined with 5-FU." (PMID 33925400, 2021). "In our previous study, we reported increased levels of IL-4, IL-6, IL-10, and TGF-β detected in the peripheral blood of lung adenocarcinoma patients." (PMID 33167343, 2020). "We assess the effect of lung adenocarcinoma cells on TAM through detecting the expression of SHP2, p- STAT1, p-STAT3, p-STAT5, p-STAT6, IL-4, IL-10, Cathepsin-L, Cathepsin-S, Cathepsin-K and Arginase-1 in each group of THP1 cells cocultured with and without A549 cells by western blot." (PMID 38747738, 2024). "CD4+CD25+CD127− Treg cells from the control groups and lung adenocarcinoma patients did not produce IL-10 (data not shown)." (PMID 26582240, 2015). "We found that, in lung adenocarcinoma patients, the suppressor function of Treg cells is not mediated by IL-10." (PMID 26582240, 2015). "Thus, our results show that CD4+CD25+CD127− Treg cells from the smoking and nonsmoking groups and from lung adenocarcinoma patients did not mediate suppressor activity by IL-10 production; nevertheless, CTLA-4 may be involved in the suppressor function." (PMID 26582240, 2015).